IL13 (interleukin 13)
Diseases named in the same sentence as IL13 in open-access papers (continued):
Sharing a sentence is not in itself a finding about the gene and the disease.
eczema (35 papers, 2011 to 2025). "Conversely, in eczema, conventional DCs (cDCs) are known to induce a Th2-cell-associated immune response, resulting in T-cell secretion of IL-4, IL-5, IL-9, and IL-13." (PMID 41009640, 2025). "AD is also an immune system skin disorder, and the secretion of cytokines, especially IL-4, IL-12, and IL-13, causes barrier defects and inflammation, resulting in the clinical features of eczema." (PMID 37569742, 2023). "This is the first study to report this association between IL13 in colostrum/human milk and eczema and/or food adverse events in children at 12 months of age." (PMID 28538696, 2017). "Preliminary univariate analysis showed detectable interleukin (IL) 2 and IL13 in HM to be associated with less eczema." (PMID 28538696, 2017). "In contrast, if detectable levels of IL13 were present in HM, it was associated with a reduced risk OR 0.18 (95% CI 0.04–0.92) of eczema development." (PMID 28538696, 2017). "Several genetic association studies have examined relationships between single nucleotide polymorphisms (SNPs) in the IL13 gene and eczema, and have provided contradictory results." (PMID 22013915, 2011). "Our findings suggest that the IL13 SNP rs1800925 is significantly associated with eczema in Japanese young adult women." (PMID 22013915, 2011). "Our previous study of Japanese children aged 3 years observed that both IL13 SNPs rs1800925 and rs20541 were significantly associated with the risk of eczema." (PMID 22013915, 2011). "We investigated the relationship between the IL13 SNPs rs1800925 and rs20541 and the risk of eczema in Japanese young adult women." (PMID 22013915, 2011). "Several genetic association studies have examined the relationships between single nucleotide polymorphisms (SNPs) in the IL13 gene and eczema, and have provided contradictory results." (PMID 22013915, 2011). "Likewise, it is known that low levels of IL-13 in colostrum and mature milk are associated with less eczema in early life." (PMID 30150532, 2018). "Despite this, higher TGFβ and IL13 did associate with eczema." (PMID 28538696, 2017). "In the discovery step, to determine whether IL13 (rs20541) and STAT6 (rs1059513) SNP genotypes have an interactive effect on the risk for eczema, four genetic models (co-dominant, dominant, recessive, and additive) were used to test for statistical interaction (IL13 × STAT6) in the IOW study." (PMID 23815671, 2013). "This is a negative regulator of pro-inflammatory cytokines, which causes a decrease in the inflammatory mediator’s response, such as IL-4 and IL-13, to prevent eczema." (PMID 41011120, 2025). "Experimental studies demonstrate its capacity to suppress nuclear factor‐κB‐mediated inflammatory pathways, reducing key cytokines such as IL‐4 and IL‐13, which drive eczema pathogenesis." (PMID 41292677, 2025). "Conversely, the clinical appearance of eczema is more uniform and characterised by a strong Th2 component involving IL-4 and IL-13 over-production." (PMID 41009640, 2025). "Dupilumab, an anti-IL-4Rα antibody that blocks IL-4 and IL-13 signaling, was approved for treatment of moderate to severe eczema (AD) in the United States in 201725." (PMID 40312358, 2025). "Monoclonal antibodies targeting allergic immune effectors, including omalizumab (IgE), dupilumab (IL-4 and IL-13), reslizumab, benralizumab, and mepolizumab (IL-5), have shown efficacy in treating the eczema and other allergic manifestations." (PMID 37727514, 2023). "In summary, the data presented in this study suggest that the four‐way gene model involving IL13 rs20541, IL4 rs2243250, ADRB2 rs1042713, and FCER1B rs569108 was significantly associated with the development of eczema in Chinese Han toddlers." (PMID 33277970, 2021). "The four‐gene model involving IL13 rs20541, IL4 rs2243250, ADRB2 rs1042713, and FCER1B rs569108 was significantly associated with the development of eczema in Chinese Han toddlers." (PMID 33277970, 2021).
eczema (continued). "The pathogenesis in eczema is complex, and many different cytokines are involved, such as IL-4, IL-5, IL-13, and IL-17." (PMID 33815560, 2021). "When unadjusted levels of growth factors and detectability of cytokines were assessed, we found that detectable IL13 and IL2 in breast milk were significantly less often associated with eczema at 6 months." (PMID 28538696, 2017). "The current study demonstrates that gene-gene interaction (epistasis) between IL13 and STAT6 polymorphisms contributes significantly to the genetic determination of eczema in two independent British epidemiological studies." (PMID 23815671, 2013). "Our investigation demonstrates an important combined effect of genetic variants within IL13 and STAT6 genes on eczema risk." (PMID 23815671, 2013). "The current study investigated the association of SNPs in IL13 (rs20541) and STAT6 (rs1059513) genes separately and jointly (gene-gene interaction) on the risk for eczema in two independent population-based studies." (PMID 23815671, 2013). "Our search of the literature indicated a lack of studies investigating the possible interaction between genetic variants in IL13 and STAT6 genes in relation to eczema risk." (PMID 23815671, 2013). "(c) The immunological system of eczema focused on T helper type 2 (Th2) cell-derived cytokines, including interleukin (IL)-4 and IL-13, and keratinocyte-derived cytokines, as well as thymic stromal lymphopoietin (TSLP) and IL-33, which contribute to Th2-mediated skin inflammation in AD." (PMID 41011120, 2025). "We report that scratching behavior but not doctors diagnosed eczema among infants was associated with higher levels of maternal serum but not breast milk IL-5, IL-6, and IL-13 cytokines." (PMID 27222655, 2016). "Scratching but not doctors diagnosed eczema was associated with higher levels of maternal IL-5, IL-6, and IL-13 during pregnancy." (PMID 27222655, 2016). "In the first exploratory step analyzing main effects only, under a co-dominant model, the AG and AA genotypes of IL13 rs20541 were not statistically significantly associated with eczema when compared to the reference genotype GG in both populations." (PMID 23815671, 2013). "In the dominant model, individuals carrying the AG or AA genotype of IL13 SNP rs20541 did not have increased risk of eczema when compared to those with the GG genotype in either population." (PMID 23815671, 2013). "Log-binomial regressions were applied to (i) account for the interaction between IL13 (rs20541) and STAT6 (rs1059513) polymorphisms and (ii) estimate the combined effect, in terms of risk ratios (RRs), of both risk factors on the risk of eczema." (PMID 23815671, 2013). "However, a consistent significant statistical interaction under a dominant genetic model between IL13 (rs20541) and STAT6 (rs1059513) on the risk of eczema was demonstrated in both studies." (PMID 23815671, 2013). "Our aim was to investigate whether SNPs in IL13 and STAT6 genes, which share a biological pathway, have an interactive effect on eczema risk." (PMID 23815671, 2013). "The purpose of this study was to determine whether an interaction between rs20541 in IL13 and rs1059513 in STAT6 on eczema risk exists." (PMID 23815671, 2013). "The current study suggests that IL13 SNP rs1800925, but not rs20541, is significantly associated with the risk of eczema in Japanese young adult women." (PMID 22013915, 2011). "Typical therapy for both eczema and EoE includes medications, such as steroids and dupilumab (a monoclonal antibody against IL4 and IL13), known to also be effective in Th2-driven atopic inflammation." (PMID 36118171, 2022). "IL4, IL13, IL1RL1, IL18R1 and TSLP are also the only proteins found to be common to eczema and rhinitis." (PMID 28598986, 2017). "Th2 cytokines, such as IL-13 and transcription factor STAT6 are key elements in the inflammatory response that characterize allergic disorders, including eczema." (PMID 23815671, 2013).
eczema (continued). "This study adds to the current knowledge of genetic susceptibility by demonstrating for the first time an interactive effect between SNPs in IL13 (rs20541) and STAT6 (rs1059513) on the occurrence of eczema in two independent samples." (PMID 23815671, 2013). "Our study adds to the current knowledge of genetic susceptibility by demonstrating for the first time an interactive effect between SNPs in IL13 (rs20541) and STAT6 (rs1059513) on the occurrence of eczema in two independent samples." (PMID 23815671, 2013). "Huangbo has also become a staple for eczema treatment, as it could decrease mRNA expressions of proinflammatory cytokines (like IL-1β, TNF-α, IL-17, IL-4, and IL-13)." (PMID 41311842, 2025). "In terms of efficacy, data from clinically used drugs strongly suggest that targeting IL-13 only, as opposed to IL-13 and IL-4, may be effective in eczema while being more selective." (PMID 30759882, 2019).
chronic obstructive pulmonary disease (34 papers, 2013 to 2025). A chronic and progressive lung disorder characterized by the loss of elasticity of the bronchial tree and the air sacs, destruction of the air sacs wall, thickening of the bronchial wall, and mucous accumulation in the bronchial tree. "In chronic inflammatory lung disease, pathogenic IL-13 producing macrophages are stimulated by a CD1d-dependent iNKT cell interaction both in experimental models as well as in chronic obstructive pulmonary disease (COPD) patients." (PMID 37818376, 2023). "One study shows a remarkable example of a pathogenic role of IL-13 in chronic obstructive pulmonary disease (COPD) that underscores the effect of M2 macrophages." (PMID 26962470, 2015). "Results from the phase I clinical trials showed that Tozorakimab significantly reduced serum levels of pro-inflammatory cytokines, particularly IL-5 and IL-13, in patients with chronic obstructive pulmonary disease." (PMID 40764944, 2025). "IL13 polymorphism is associated with chronic obstructive pulmonary disease (COPD)." (PMID 36497047, 2022). "An association between plasma concentration of IL-13 and increasing severity of airflow obstruction and diffusion capacity of carbon monoxide (DLCO) was reported in human subjects suffering from chronic obstructive pulmonary disease." (PMID 34418598, 2021). "One such disease state is allergic airway inflammation caused by type 2 (T2) cytokines (IL-4, IL-5, IL-13), which is common in both children and adults and has been associated with the development of both asthma and chronic obstructive pulmonary disease (COPD) in a subgroup of patients." (PMID 33046696, 2020). "Interleukin (IL)-13, a T-helper type 2 cytokine, plays a critical role in the development of chronic obstructive pulmonary disease (COPD)." (PMID 23874547, 2013). "Increased amounts of iNKT cells and of IL-13 producing macrophages have been detected not only in mice, but also in patients with chronic obstructive pulmonary disease (COPD), supporting the involvement of the iNKT cell/macrophage crosstalk in the lung pathophysiology." (PMID 30369933, 2018). "Aberrant TSLP, IL-4, and IL-13 levels and activities in the airway lead to the onset and sustaining of atopic asthma and chronic obstructive pulmonary disease (COPD)." (PMID 41294800, 2025). "Azithromycin decreases the secretion of IL-4, IL-5, IL-13, and IL-17A from peripheral blood mononuclear cells in patients with chronic obstructive pulmonary disease (COPD)." (PMID 37357527, 2023). "This microfluidic model was utilized to mimic the pathophysiology of asthma and chronic obstructive pulmonary disease (COPD) and examine the effect of interleukins (IL)-13 treatment." (PMID 35794768, 2023). "It has been directly reported to be functionally correlated with IL-13 and IL-17 in focal regions surrounding airway smooth muscles at the transcriptomics level and is further pathologically correlated with several chronic lung diseases, including chronic obstructive pulmonary diseases." (PMID 33519902, 2020). "Pulmonary expression of transgenic IL-13 in adult lungs resulted in a chronic obstructive pulmonary disease (COPD) phenotype with inflammation, mucus metaplasia and matrix metalloproteinase- and cathepsin-dependent emphysema." (PMID 23874547, 2013). "Analysis of primary bronchial epithelial cells (PBECs) from patients with severe chronic obstructive pulmonary disease (COPD) revealed significantly elevated TNF-α and IFN-γ levels, reduced IL-4 and IL-13 levels, and elevated Th1-dominated cytokine responses." (PMID 38495892, 2024). "The IL-4/IL-13 antagonist, IgG1, and an anti-IgE monoclonal antibody (Omalizumab®) have been administered as dried powder inhaler preparations for asthma, chronic obstructive pulmonary disease (COPD), or other related lung diseases." (PMID 30126135, 2018).
pancreatic cancer (32 papers, 2011 to 2025). "The aim of this review was to summarize the present knowledge about the IL-4/IL-13 cytokine-receptor system focusing on pancreatic cancer to help to develop attractive targets for novel diagnostic and therapeutic approaches for pancreatic cancer." (PMID 33804263, 2021). "We have previously demonstrated that IL-13-PE is a powerful anti-cancer agent, causing regression of IL-13Rα2-positive human tumors derived from variety of human cancers including pancreatic cancer." (PMID 21477288, 2011). "We also demonstrate that HDAC inhibitors when combined with IL-13-PE cause more dramatic tumor responses than those caused by either agent alone in two pancreatic cancer models." (PMID 21477288, 2011). "In addition, increased IL-13 levels were correlated with elevated levels of myeloid-derived suppressor cells that were associated with increased risk of death from pancreatic cancer." (PMID 33804263, 2021). "In addition, prevention of macrophage polarization to a M2 subtype by an IL-13 neutralizing antibody diminished fibrosis, which is associated with pancreatic tumor proliferation and progression." (PMID 29379802, 2017). "IL-4 and IL-13 are reported to promote pancreatic cancer progression via Type II IL-4 receptor signaling, which enhances tumor proliferation, invasion, and immune escape in pancreatic cancer." (PMID 41384105, 2025). "This process recruits and activating Th2 and ICL2 cells, which, in turn, can facilitate the progression of pancreatic cancer through the secretion of cytokines such as IL-4 and IL-13." (PMID 39814702, 2025). "Previous studies indicate that in pancreatic cancer, activated mast cells can stimulate the proliferation of fibroblasts, specifically pancreatic stellate cells, through the secretion of IL-13 and tryptase." (PMID 39814702, 2025). "For example, activated mast cells promote tumor growth through tryptase and IL-13 in pancreatic cancer." (PMID 37042867, 2023). "The expression of IL-4 and IL-13, as well as IL-4Rα and IL-13Rα1 receptor chains, was shown in several cultured pancreatic cancer cell lines by us and by other research groups." (PMID 35409019, 2022). "Changes in the downstream signalling of the IL-4 and IL-13 axis in pancreatic cancer cells were investigated in Capan-1." (PMID 35409019, 2022). "Exogenous IL-4 and IL-13 enhanced the growth of pancreatic cancer cells, while IL-4-/IL-13-neutralizing antibodies counteracted this effect." (PMID 35409019, 2022). "IL-4 and IL-13 act on pancreatic cancer cells mainly through their receptor heterodimers IL-4-receptor-alpha (IL-4Rα) and IL-13Rα1, termed type II IL-4R, via signal pathways of STAT3/6, IRS-ERK/PI3K-Akt and mTOR." (PMID 35409019, 2022). "Exogenous IL-4 and IL-13 enhanced the growth of pancreatic cancer cells in a dose-dependent manner, which was inhibited by IL-4-/IL-13-neutralizing antibodies." (PMID 35409019, 2022). "The related inflammatory cytokines IL-4 and IL-13 can regularly be detected at increased levels in the microenvironment of pancreatic cancer." (PMID 35409019, 2022). "Now, increasing evidence indicates salient activities of IL-4, IL-13 and their specific receptor complex IL-4Rα/IL-13Rα1 in carcinomas including pancreatic cancer." (PMID 35409019, 2022). "Previous results are indicative of a contributing role of the IL-13/IL-13Rα1 axis to pancreatic cancer." (PMID 35409019, 2022). "IL13-PE displayed significant inhibition on tumor growth, leading to longer survival time, in both orthotopic and xenograft mouse models of pancreatic cancer." (PMID 33804263, 2021). "A significant elevation of IL-13 protein detected in the plasma of pancreatic cancer patients was reported." (PMID 33804263, 2021). "Increasing evidence supports the critical roles for IL-4 and IL-13 in the progression of pancreatic cancer." (PMID 33804263, 2021).